CCND1 (cyclin D1)
Diseases named in the same sentence as CCND1 in open-access papers (continued):
Sharing a sentence is not in itself a finding about the gene and the disease.
cancer (continued). "It suggests that CCND1 870A allele is more likely to contribute to cancer development through promoting the transition between G1 and S phases." (PMID 24222746, 2013). "The overexpression of Cyclin D1 is a common event in cancer cells and can be caused either by a gene amplification or by a defective regulation at the posttranslational level." (PMID 23710216, 2013). "It has been demonstrated that oncogenic actions of cyclin D1 are predominantly nuclear in many cancers, as carcinogenic mutations and deletions often occur at the T286 site, which controls cyclin D1 protein turnover and nuclear export." (PMID 23786849, 2013). "Cyclin D1 positively regulates progesterone receptor expression levels and this has been postulated to be a factor that contributes to the increased risk of cancer development following hormonal exposure." (PMID 24575359, 2012). "Frequently, during cancer development the increase in cell proliferation rate is associated with overexpression of the cyclin D1 as a result of chromosomal translocation or gene amplification." (PMID 22292081, 2012). "More recent studies have demonstrated that overexpression of cyclin D1 is linked to the development of various cancers." (PMID 22359572, 2012). "In summary, development of tamoxifen resistant hyperplasia and cancer was associated with expression of ERα and cyclin D1." (PMID 24575359, 2012). "Recently, several meta-analyses have been conducted to assess the association of CCND1 G870A polymorphisms with cancer risks." (PMID 23170138, 2012). "The E2F genes are deregulated in many cancers by various mechanisms like overexpression of cyclin D1, loss of pRB, and expression of human papillomavirus (HPV) oncoprotein E7, to name a few." (PMID 23320178, 2012). "Previously, a common functional polymorphism, G870A, of CCND1 has been widely studied as a possible low-penetrant susceptibility allele for various cancers." (PMID 23170138, 2012). "Further cyclin D1 G/A870 polymorphism has been implicated as a modulator of cancer risk and/or poor prognosis in human disease." (PMID 22770229, 2012). "Ectopic expression of N24 also inhibited cyclin D1 and E promoter activity and caused G0/G1 phase arrest in several cancer cell lines." (PMID 22876838, 2012). "Cyclin D1 loss following CCT020312 treatment was observed across a range of different human cancer cell lines, including those known to express aberrantly high amounts of this cyclin." (PMID 22253692, 2012). "The obvious association of Cyclin D1 with cancer has led the investigators to uncover its oncogenic properties." (PMID 21347341, 2011). "Prostaglandin A2 (PGA2) is an experimental anti-cancer agent associated with decreased levels of cyclin D1 and decreased proliferation of cancer cells." (PMID 21835052, 2011). "HPV-HNCs up-regulated, relative to HPV+ cancers, a small set of cell cycle-specific genes, including cyclin D1/D2 (CCND1 and CCND2; G1 associated) and cyclin A1 (CCNA1)." (PMID 21447181, 2011). "The loss of regulatory control of the cellcycle, which leads to unrestrained cell proliferation, is a hallmark of cancer.Cyclin D1 is overexpressed in breast, liver, lung and brain cancers." (PMID 21455311, 2011). "Because cyclin D1 and Twist are two important down-stream effectors of Myc and their biological functions are associated with the invasive/tumorigenic ability of cancer cells, cyclin D1 and Twist protein levels were determined by Western blot analysis." (PMID 21575199, 2011). "In conclusion, our results suggest hUCBSC can attenuate uncontrolled cell cycleprogression, which is a hallmark of cancer, by down regulating the expression levelsof cyclin D1 and its partner kinases Cdk 4 and Cdk 6 at the cell cycle level." (PMID 21455311, 2011).
cancer (continued). "Cyclin D1 over-expression is associated with numerous cancers and is crucial for the transition from G1 to S phase in the mammalian cell-cycle." (PMID 21347341, 2011). "Cyclin D1, a key regulator of G1 to S phase progression, is tightly associated and aberrantly expressed in numerous human cancers." (PMID 21347341, 2011). "Cancer cells show overexpression of this cyclin D1 and thus it has been linked to the development and progression of cancer." (PMID 22069560, 2010). "Cyclin D1 expression, the most studied D-cyclin in cancer cell has been associated with anchorage-independent growth, tumorigenicity, angiogenesis, hypoxia response and resistance to chemotherapeutic agents." (PMID 20113529, 2010). "According to clinical sample studies, Cyclin D1 overexpression has been found in a variety of carcinomas, and have been linked to the early onset, progression and metastasis of tumors." (PMID 20105337, 2010). "Cyclin D1 is an important regulator of G1 to S-phase transition and overexpression of cyclin D1 has been linked to the development and progression of cancer." (PMID 19878607, 2009). "On the one hand fibronectin has been shown to stimulate proliferation of cancer cells, and this was associated with increased cyclin D1 and decreased p21Cip1 levels." (PMID 19473496, 2009). "Wnt target genes include cyclin D1 and c-myc, both of which are also associated with proliferation and are over-expressed in several cancers." (PMID 19874621, 2009). "In this study, we used luciferease reporter assays to validate microRNAs that can silence cyclin D1 (CCND1) because CCND1 is a well known proto-oncogene implicated in a variety of types of cancers." (PMID 19538740, 2009). "Cyclin D1 is an important regulator of cell cycle progression and overexpression of cyclin D1 has been linked to the development and progression of cancer." (PMID 17407548, 2007). "It is also possible that while the loss of SCFFBX4-αB crystallin allows the accumulation of cyclin D1 during cancer development, the continued expression of FBXW8 is required to maintain levels below the threshold required to repress DNA replication." (PMID 17407548, 2007). "Recent functional analyses of an established cyclin D1 splice variant, cyclin D1b, revealed that the cyclin D1b isoform harbors unique activities in cancer cells." (PMID 16863592, 2006). "Up-regulation of Ccnd1, Ccnd3, and Jun mRNA (all transcriptional targets of Wnt signaling) are suggestive of increased risk to human cancer." (PMID 16203246, 2005). "It has been suggested that cancer cells can escape from G1/S arrest induced by p16, RB loss and Cyclin D1 amplification, via mechanisms that can over-ride the braking effect." (PMID 14583787, 2003). "Cyclin D1 and its associated CDKs are promising therapeutic targets in human cancers." (PMID 40408472, 2025). "One such compound, PRI-724, binds with high affinity to the N-terminus of CBP and influences the expression of β-catenin target genes associated with cancer cell survival (e.g., survivin, c-Myc, and cyclin D1) while leaving p300-mediated β-catenin activity unaffected." (PMID 41227355, 2025). "Specifically, CCND1 is associated with six drugs (abemaciclib, bexarotene, lapatinib, palbociclib, ribociclib, tamoxifen), which are primarily used for cancer treatment but may also influence PSO through CCND1 modulation." (PMID 39830966, 2025). "Cyclin D1 overexpression promotes RB phosphorylation, releasing E2F transcription factors that drive S-phase entry and uncontrolled cellular proliferation—a hallmark of cancer." (PMID 40507823, 2025). "Cyclin D1 (encoded by CCND1) is frequently overexpressed in cancers by a variety of mechanisms." (PMID 40608419, 2025). "Interestingly, YB-004 inhibited cyclin D1 expression, thereby interfering with the cell cycle of cancer cells and inhibiting HR, resulting in the HR-deficient phenotype of cancer cells." (PMID 40083696, 2025).
cancer (continued). "Cyclin D1 and cyclin E1 are regulators of G1–S-phase cell cycle progression, are often constitutively expressed, and are associated with pathogenesis and tumorigenesis in most human cancers." (PMID 39940838, 2025). "Cyclin D1 (encoded by CCND1) is a well-known oncoprotein overexpressed in cancer; however, its role in RS is unknown." (PMID 40608419, 2025). "Therefore, we examined the expression of circFOXK2 and CCND1 as well as their association in other cancer types." (PMID 40233410, 2025). "Furthermore, β-catenin is a central component of the Wnt signaling pathway, modulating the transcription of several downstream genes such as MMPs, c-Myc, cyclin D1, and vimentin, which has been implicated in cancer progression and therapeutic resistance." (PMID 41304843, 2025). "Upregulation of other cancer-associated genes in MPOSE – such as Ccnd1, Btc, Ankrd1, Oraov1, Cd44 and Ifitm3 – as well as possible DNA mutations or fusions, may also contribute to tumorigenic differences and warrant further investigation." (PMID 40642792, 2025). "To summarize, this study demonstrated that CCND1 rs9344 may be considered a candidate biomarker for cancer susceptibility and therapeutic outcome in certain patient subgroups in Chinese population." (PMID 38589850, 2024). "High levels of cyclin D1 are associated with the development and progression of cancer." (PMID 39206407, 2024). "These CCND1 methylation patterns may also be used as a diagnostic and prognostic sign in these types of cancer." (PMID 39188436, 2024). "Notably, mutations and overexpression of CCND1 alter cell cycle progression and are observed frequently in a variety of human cancers." (PMID 38642129, 2024). "For example, lncRNA miR503HG suppresses cyclin D1; known to boost expressions of the G1/S cell cycle which is found to be a leading cause in cancer progression, and lowering levels of miR503HG is attributable to poor prognosis and survival in cancer patients." (PMID 38745221, 2024). "Delving deeper into the mechanistic significance of this study, there is a clear correlation of dysregulated activity of SR proteins (major downstream targets of CLKs) contributing to increased oncogenic splice variants such as cyclin d1 and vegf transcripts across several cancers." (PMID 39770502, 2024). "Cyclin D1 overexpression has been linked to cancer development and progression." (PMID 39296438, 2024). "This study suggests that in the Chinese population, CCND1 rs9344 could potentially serve as a candidate biomarker for cancer susceptibility and treatment outcomes in specific subgroups of patients." (PMID 38589850, 2024). "The lower methylation of CCND1 is associated with poor prognosis in several cancers." (PMID 39188436, 2024). "CCND1 has many mutation types with different mutation frequencies in human cancers." (PMID 37024471, 2023). "Over-expression of CCND1 can lead to cancer and the rs9344 in this gene increases the risk for BC." (PMID 38025894, 2023). "Similarly, cyclin D1 is a proto-oncogene that is overexpressed in different types of cancer and can cause uncontrolled cell proliferation." (PMID 37465088, 2023). "On the other hand, the reduction of CCND1 in human cancer cells may decrease the homologous recombination and cause higher sensitivity of cells to DNA damage." (PMID 37316878, 2023). "The induction of numerous biosynthetic pathways likely underlies the ability of cyclin D1 to promote hepatocyte proliferation and liver growth in the absence of other mitogenic stimuli and may contribute to its role in cancer." (PMID 38152849, 2023). "In other cancers, CCND1 mutations promote ibrutinib resistance in mantle cell lymphoma." (PMID 36980210, 2023).
cancer (continued). "In the present study, we explored computational simulations through bioinformatics analysis and identified the overexpression of c-Met/GSK3β/MYC/CCND1 oncogenic signatures that were associated with cancer progression, drug resistance, metastasis, and poor clinical outcomes in CRC." (PMID 36672275, 2023). "The dysregulation of the CCND1 isoforms is associated with multiple human cancers." (PMID 37024471, 2023). "Similarly, Cyclin D1 is overexpressed in most malignant tumors and is associated with a poor prognosis." (PMID 38031136, 2023). "However, it has to be noted that the expression of Fascin-1 is naturally enhanced in cancer cell lines.Furthermore, loss of Fascin-1 in melanoblasts was associated with less Cyclin D1-positive nuclei." (PMID 37015875, 2023). "CCND1 G870A polymorphism results in the formation of CCND1a and CCND1b,51 but the role of CCND1a and CCND1b variants in cancer chemoresistance remains unknown." (PMID 36915230, 2023). "Accumulating evidence shows that CCND1 amplification is a possible risk factor for many cancers." (PMID 35844619, 2022). "Furthermore, enhanced expression of cyclin D1 instigates profound proliferation of cells by altering the cell cycle′s homeostatic regulatory mechanisms and acts as a risk factor for the onset of cancers." (PMID 35054507, 2022). "Since cyclin D1 up-regulation is a frequent event also in benign sporadic PAs (20-40% of cases), the over-expression of this protein cannot be used as a hallmark to distinguish benign from malignant tumors." (PMID 35282432, 2022). "Cyclin D1 controls cell cycle progression, and its overexpression is associated with many cancers." (PMID 35566382, 2022). "Cyclin D1 is considered a proto-oncogene, and its sustained high expression will shorten the G1 phase, causing premature transition to the S phase and subsequently uncontrolled cell proliferation and cancer." (PMID 35497881, 2022). "The presence of neck lymph node metastases increased the likelihood of death due to cancer by over five times; high histological grading (G3) resulting in increased risk of death over 2.5-fold and also high expression of the Cyclin D1 protein (above the median)." (PMID 35626215, 2022). "The β-catenin protein serves as a transcription factor coactivator, T cell factor, and lymphoid enhancer factor upon entering the nucleus to activate transcription of the β-catenin-dependent genes such as the cyclin D1 gene, CCND1, whose overexpression is linked to cancer." (PMID 35480118, 2022). "Abnormal dysregulation of the CDK4/6-cyclin D1 complex is a hallmark of cancer." (PMID 34395284, 2021). "Interestingly, TCGA (cBioPortal, METABRIC, Nature 2012 & Nat Commun 2016) data analyses show that a proportion of these human cancers show increased or amplified cyclin D1, which is encoded by the CCND1 oncogenic gene." (PMID 33808757, 2021). "Cyclin D1 overexpression has been associated with a number of cancers including MTC." (PMID 34209165, 2021). "In addition, Ccnd2, Ccnd1, and Raf1 are targets of the downregulated miR-15b-5p in exposed mice, and these targets are implicated in cancer and cell cycle regulation." (PMID 34199666, 2021). "As known, CASP3 is a key enzyme in the execution of apoptosis and CCND1 codes for the cyclin D1 protein to affect the cell cycle progression, both of which were reported to contribute to many types of cancers and closely associated with cell motility, invasion, and metastasis." (PMID 33494738, 2021). "Importantly, cyclin D1 dysregulation has previously been associated with a number of cancers and is linked to a poorer prognosis; however, there is yet to be an approved therapy which targets this protein." (PMID 34722257, 2021). "Cyclin D1 has been found highly expressed in cancer tumors and was associated with metastasis." (PMID 34158560, 2021). "It has been reported that the overexpression of cyclin D1 is associated with cancers." (PMID 33803555, 2021).
cancer (continued). "Cyclin D1, best known for driving cell cycle from G1 to S phase, is also involved in DNA damage repair in association with Rad51, and its inhibition impairs DNA repair capacity leading to sensitization of cancer cells to cisplatin." (PMID 33530952, 2021). "In the DKFZ Classifier, benign and malignant GCTBs cluster together; however, directed analysis of methylation data of these subtypes not only allowed them to be separated, but also implicated CCND1 as a likely cancer driver gene in the malignant transformation of GCTB." (PMID 33949149, 2021). "CCND1-associated chromosomal aberrations could cause multiple occurrences of lymphocyte malignant tumors, rack mounting, and multiple occurrences." (PMID 34335821, 2021). "STAT3 is closely associated with pathogenesis of various cancers by regulating the expression of critical genes for survival, proliferation, and angiogenesis, such as Bcl-2, Bcl-xL, Mcl-1, CCND1, and VEGF, which were important for survival, proliferation, and angiogenesis." (PMID 34335938, 2021). "However, a recent study, which assessed abemaciclib sensitivity across many human cancer cell lines, suggested that loss of p16 and low cyclin D1 expression were associated with abemaciclib resistance." (PMID 32899250, 2020). "The suppression of nuclear translocation of β-catenin into gastric cells along with the expression of the β-catenin target survival genes c-myc and cyclin D1 along with induction of apoptosis has recently been implicated as a potential mechanism of anti-cancer therapy." (PMID 33023180, 2020). "We speculated that upregulations of p-Stat1 in ESCC cancer cells may cause an increase of proteasomal degradation of cyclin D1, resulted in the less dramatic upregulations of protein levels of cyclin D1 in human ESCC tissue samples." (PMID 33046973, 2020). "Mycophenolic acid, an immunosuppressant, can inhibit proliferation and induce apoptosis in cancer cells, which may be caused by inhibition of upregulation of CCND1 and the PI3K/AKT/mTOR pathway." (PMID 32733557, 2020). "Since eIF4E protein is overexpressed in 30% of cancers, it acts as a reference translation initiation factor associated with the translation of genes involved in proliferation, e.g. cyclin D1 or c-myc, stimulating proliferation of cancer cells when overexpressed." (PMID 31825993, 2019). "Interestingly, using the expression of PCNA and CCND1, two hallmark cell-cycle genes, as a proxy for proliferation status, we did not observe a significant difference between high- and low-proliferating cancer cells." (PMID 31501864, 2019). "Deregulation of cyclin D1 is associated with various types of cancers." (PMID 32010690, 2019). "We exploited and mined the publicly available data of the Cancer Genome Atlas Project and other published exome sequencing studies to interrogate the frequency, spectrum and oncogenic effects of CCND1 mutations across of a large number and diverse set of human cancers." (PMID 29969496, 2018). "SKE at doses of 150 and 200 could reduce the protein expression of cyclin D1 in MCF-7 cancer cell thus causing reduction in the growth and proliferation of these cells." (PMID 29755565, 2018). "In agreement, our real-time PCR analysis demonstrated that the mRNA level of oncogenic genes including cMyc, cyclin D1 and cancer stem cell associated markers, CD44, β-catenin and Axin-2 was all up-regulated in the spheres as compared to their parental counterparts." (PMID 30005681, 2018). "Thus, we performed a meta-analysis to explore the association between CCND1 variant and overall cancer risk in Indian population." (PMID 30361291, 2018). "Exome studies containing CCND1 mutations with respective cancer type and CCND1 mutation frequency." (PMID 29969496, 2018). "The present data could be helpful in enriching the existing knowledge with respect to involvement of CCND1 polymorphism and cancer susceptibility in Indian population." (PMID 30361291, 2018).